ATM (ATM serine/threonine kinase)
Diseases named in the same sentence as ATM in open-access papers (continued):
Sharing a sentence is not in itself a finding about the gene and the disease.
chronic pancreatitis (2 papers, 2021 to 2025). A chronic inflammatory process causing damage and fibrosis of the pancreatic parenchyma. "The patient exhibited granulomatous dermatitis and chronic pancreatitis, features rarely described in children with ATM deficiency, emphasizing the disorder’s phenotypic diversity." (PMID 41300699, 2025). "In ATM deficiency, granulomatous dermatitis and chronic pancreatitis have been only sporadically reported in children; their co-occurrence in our patient underscores the breadth of inflammatory manifestations and may inform anticipatory guidance." (PMID 41300699, 2025).
Cirrhosis (2 papers, 2021 to 2025). A chronic disorder of the liver in which liver tissue becomes scarred and is partially replaced by regenerative nodules and fibrotic tissue resulting in loss of liver function. "Seven of 12 ATM-mutant patients (58%) had ILD, 3 of 12 (25%) had cirrhosis, and 4 (33.3%) died of complications of TBD." (PMID 40179146, 2025).
clear cell carcinoma (2 papers, 2020 to 2021). "The role of downregulation of ATM signaling in clear cell carcinomas is not reported, although high ATM protein and mRNA in HGS carcinomas correlates with poor survival and platinum resistance." (PMID 33415077, 2020).
co-infection (2 papers, 2010 to 2023). "It is possible that loss of MRN during AAV/Ad co-infection limits the ATM response during AAV infection." (PMID 20949077, 2010). "In both HeLa and 293 cells, AAV2 and Ad co-infection induces the phosphorylation of ATM, DNA-PKcs, RPA32, and H2AX." (PMID 36719192, 2023).
colitis (2 papers, 2014 to 2015). Inflammation of the colon. "In other murine models, e.g. an experimental model of colitis, or acute inflammation, ATM deficiency also increases production of pro-inflammatory mediators and regulates leukocyte trafficking to inflammatory sites." (PMID 24884546, 2014). "There are two potential explanations for this; firstly, these cofactors have ATM-independent roles that contribute to the development of colitis." (PMID 26544571, 2015). "Our data also confirmed the reported mild sensitivity of ATM-/- to DSS induced colitis." (PMID 26544571, 2015).
colorectal adenoma (2 papers, 2019). An adenoma that arises from the colon or rectum. "We identified genes with somatic mutations in the normal-colorectal adenoma samples, APC, CTNNB1, LRP5, FBXW7, and ATM, which overlapped with the TCGA data." (PMID 31336886, 2019).
dementia (2 papers, 2013 to 2023). Loss of intellectual abilities interfering with an individual's social and occupational functions. "Expression of ATM and some of its downstream effectors was increased during progression of dementia and with increasing severity of AD neuropathology in the grey matter of the STG." (PMID 23861893, 2013). "The expression of CCL-checkpoint and DNA damage response genes: MDM4, ATM and ATR was strongly upregulated and associated with progression of dementia (cognitive dementia rating, CDR), appearing as early as questionable or mild dementia (CDRs 0.5–1)." (PMID 23861893, 2013). "Neuronal cell cycle checkpoint proteins, together with the DNA damage response genes Mouse double minute 4 homolog (MDM4), Ataxia-telangiectasia mutated (ATM) and ATM- and Rad3-Related (ATR), are strongly up regulated and associated with the progression of dementia." (PMID 36918783, 2023). "In conclusion, ATM may be a crucial link between the damaging effect of ROS and reactivation of mitotic cell cycle in dementia." (PMID 23861893, 2013). "Taken as whole, the present findings suggest that ATM upregulation and progressive decrease of TIGAR protein levels are distinctive features of dementia progression in AD." (PMID 23861893, 2013).
dengue (2 papers, 2016 to 2017). "The fact that inhibition of ATM causes loss of dengue-induced autophagy and protection validates the role of ATM as well as that of ER stress signaling as components of autophagy signaling activated by dengue." (PMID 26938301, 2016). "In this study, we evaluate how it does so; we show that dengue upregulates host pathways that increase autophagy, namely endoplasmic reticulum (ER) stress and ataxia telangiectasia mutated (ATM) signaling followed by production of reactive oxygen species (ROS)." (PMID 26938301, 2016). "Inhibition of ATM by KU55933 (ATMi) suppresses increased CHOP transcription in dengue-infected cells." (PMID 26938301, 2016). "The inhibition of ATM and subsequent autophagy by caffeine and KU55933 results in the loss of dengue-induced protection against other stressors." (PMID 26938301, 2016). "Dengue-induced ER stress is a better target for inhibiting virus-induced protection and autophagy than ATM as blocking ER stress can also reduce ROS production but the net physiological result is unclear." (PMID 26938301, 2016). "Inhibition of ER stress or ATM signaling abrogates the dengue-conferred protection against other cell stressors." (PMID 26938301, 2016). "We next examined how dengue-induced ATM activity affected autophagy after 24 h of infection." (PMID 26938301, 2016). "We also used 5 μM ATMi to measure whether ATM signaling was important to dengue-induced protection of cells; results were similar to caffeine treatment in that blockage of ATM by ATMi eliminated the protection." (PMID 26938301, 2016). "To determine whether the early activation of ATM by dengue is relevant to ER stress signaling, a regulator of autophagy, we assessed ER stress by transcription of CHOP." (PMID 26938301, 2016).
DiGeorge syndrome (2 papers, 2017 to 2019). "Disturbed distributions of lymphocyte subsets or combinations of lymphocyte subsets can also be observed in other PID cases such as patients with WAS, ATM, DOCK8 deficiency, or DiGeorge syndrome." (PMID 30886612, 2019).
epidermoid laryngeal carcinoma (2 papers, 2011 to 2020). "However, there were no reports about the antisense oligodeoxynucleotides of ATM strengthening radio-induced apoptosis of laryngeal squamous cell carcinoma grown in nude mice." (PMID 21496344, 2011).
gynecologic cancer (2 papers, 2018 to 2023). "Among prospectively detected BC or gynecological cancer phenocopies in the path_BRCA1/2 families, we found that 4/48 have pathogenic variants in high-penetrance cancer genes: two BC- and one CRC-associated gene (ATM, BRCA2 and MSH6, respectively)." (PMID 29371908, 2018).
herpes infection (2 papers, 2023 to 2025). "This has been particularly evidenced in herpesvirus infections, for which ATM and ATR DNA damage pathway proteins play beneficial roles for viral replication." (PMID 36951571, 2023). "The expansion of HSATII via the endogenous HSATII transcripts was reported not only in cancer cells but also in herpes infection, which might be via a noncanonical ATM-regulated DNA damage response." (PMID 40429892, 2025).
in situ carcinoma (2 papers, 2018 to 2021). A malignant epithelial neoplasm which is confined to the epithelial layer without evidence of further tissue invasion. "About a quarter of all ATM-related BCs and a third of CHEK2 BCs were in situ carcinomas and more than half of ATM and CHEK2-related BCs were diagnosed at stage I-II." (PMID 33919281, 2021). "About a quarter of all ATM-related BCs and a third of CHEK2 BCs were in situ carcinomas and more than half of ATM and CHEK2-related BCs were diagnosed at stage I-II (59.1% and 55%, respectively), whereas 13.6% of the ATM BCs and 15% of the CHEK2 BCs were stage III-IV." (PMID 33919281, 2021).
invasive carcinoma (2 papers, 2018 to 2022). A carcinoma that is not confined to the epithelium, and has spread to the surrounding stroma. "Of note, the patient with IPMN who had an ATM variation (c.3576 + 1G>A) was found to have an invasive carcinoma 9 years after initial surgical resection." (PMID 35171259, 2022).
Kidney Cyst (2 papers, 2021 to 2022). Abnormal fluid filled sac within the kidney, either acquired or congenital. "This study hypothesized that reducing either ATM or ATR attenuates kidney cyst formation and growth in experimental ADPKD." (PMID 33802342, 2021). "The present study aimed to begin to evaluate this hypothesis and specifically investigate whether reducing either ATM or ATR attenuates kidney cyst growth." (PMID 33802342, 2021). "In conclusion, these data suggest that CECs are resistant to DNA damage, and that the combination of cisplatin with ATM inhibitors is not an effective strategy for selectively eliminating kidney cysts in ADPKD." (PMID 36293397, 2022). "The functional significance of ATM or ATR in mediating kidney cyst growth in ADPKD is however not known." (PMID 33802342, 2021). "In conclusion, despite short-term effects on reducing renal cell proliferation, chronic progression was not altered by reducing ATM in vivo, suggesting that this DDR kinase is dispensable for kidney cyst formation in ADPKD." (PMID 33802342, 2021).
large cell lung carcinoma (2 papers, 2024). "Interestingly, the H460 large cell lung carcinoma and ATM-null H23 cell lines were considerably more sensitive to the Ku inhibition by 3392 with IC50 values of ~8 μM, a phenomenon that cannot be attributed to induction of direct DNA damage." (PMID 39409907, 2024).
leiomyoma (2 papers, 2018 to 2025). A well-circumscribed benign smooth muscle neoplasm characterized by the presence of spindle cells with cigar-shaped nuclei, interlacing fascicles, and a whorled pattern. "Two uncorrelated (r2 = 0.007) missense variants in the ATM gene, rs1801516 (Asp1853Asn) and rs1800057 (Pro1054Arg), independently associate with leiomyoma." (PMID 30194396, 2018). "The association between missense variants in ATM and leiomyoma is also unexpected." (PMID 30194396, 2018). "In one case, neither of the found P/LP variants explained the phenotype: a patient with FH-deficient leiomyoma had P/LP variants in CDH1 and ATM (case #16)." (PMID 40943312, 2025). "Four additional leiomyoma variants in our meta-analysis, one at the TERT locus, two in ATM, and one at the OBFC1 locus, have previously been associated with cancer risk." (PMID 30194396, 2018). "These same loss-of-function variants do not associate with leiomyoma risk, suggesting that the missense variants may have a mild effect on some specific functions of ATM in uterine tissue." (PMID 30194396, 2018).
liver failure (2 papers, 2020 to 2021). A liver disease characterized by the liver losing or has lost all of its function. "Ataxia telangiectasia mutated (ATM), a core component of the DNA repair system, plays critical roles in the pathological features of liver failure as well." (PMID 34180140, 2021). "For example, it was reported ATM signaling pathway plays an important protective function of causing liver failure in mice." (PMID 33330410, 2020).
lymphedema (2 papers, 2024 to 2025). Excess fluid collection in tissues, causing swelling. "No significative difference between ATM PV or predicted PV carriers and noncarriers was observed when looking at acute dermatitis (p = 0.98), dysphagia (p = 1) or lymphoedema (p = 1)." (PMID 38611095, 2024).
metastasis (2 papers, 2016 to 2018). The spread or migration of cancer cells from one part of the body (where they first appeared) to another. "Thereby, synchronous lung metastasis more frequently showed mutations in ATM, KIT, PIK3CA and SMAD4 (each with 3/5 cases as compared to 1/5 cases with metachronous liver metastases)." (PMID 27756406, 2016).
Miscarriage (2 papers, 2024). A pregnancy that ends at a stage in which the fetus is incapable of surviving on its own, defined as the spontaneous loss of a fetus before the 22th week of pregnancy.
multiple sclerosis (2 papers, 2019 to 2025). A progressive autoimmune disorder affecting the central nervous system resulting in demyelination. "Two of these, ICAM1 and ATM, are existing drug targets used in the treatment of multiple sclerosis, fatigue, orthostatic hypotension and osteoarthritis (natalizumab, caffeine and hyaluronic acid, respectively) and may provide potential targets for repositioning." (PMID 31092410, 2019).
Myocardial fibrosis (2 papers, 2013 to 2022). "Further investigations are needed to understand the role of ATM deficiency in deposition of myocardial fibrosis in response to WD." (PMID 36117462, 2022). "Recently, using ATM-/- mice, we have shown that lack of ATM induces structural and functional changes in the heart with enhanced myocardial fibrosis and myocyte hypertrophy." (PMID 24358288, 2013).
myocardial ischemia (2 papers, 2024 to 2025). A disorder of cardiac function caused by insufficient blood flow to the muscle tissue of the heart. "Tanshinone IIA can relieve the myocardial ischemia-reperfusion injury in cardiac cells by activating the ATM/GADD45/ORC pathway." (PMID 39776578, 2024).
myopia (2 papers, 2022 to 2025). "The challenges of statistical fine-mapping were exemplified by the novel discovery of the ATM gene as the possible myopia susceptibility gene." (PMID 35022715, 2022).
myxofibrosarcoma (2 papers, 2024 to 2025). A malignant fibroblastic neoplasm arising from the soft tissue. "Aberrations in ATM are present in 5% (12/255) of the PanCancer Atlas Sarcoma dataset, mostly in myxofibrosarcomas." (PMID 39594770, 2024).
neuropathy (2 papers, 2013 to 2025). A disorder affecting the nervous system that manifests with pain, tingling, numbness, and/or muscle weakness. "Indeed, we identified four families with neuropathy as the predominant or sole clinical feature, harboring variants in genes causing complex neurological syndromes, such as SPG7, FXN, and ATM." (PMID 39776111, 2025).
pharyngeal cancer (2 papers, 2011 to 2021). "Previously, we have reported an association between low ATM expression and poor patient outcome in laryngeal and pharyngeal cancers." (PMID 34068585, 2021). "In this regard, we found that laryngeal and pharyngeal cancer patients with low ATM expression exhibited a poor overall survival (OS) rate." (PMID 34068585, 2021).
Primary amenorrhea (2 papers, 2020 to 2024). "Mutations in ATM led to syndromic POI, characterized by primary amenorrhea and associated with autosomal recessive ataxia telangiectasia." (PMID 33095795, 2020). "ATM contributed to ovarian function and alterations of it results syndromic POI, characterized by primary amenorrhea." (PMID 38649916, 2024).
radiation dermatitis (2 papers, 2014 to 2025). "Short-term treatment of GDFs with retinoic acid improved radiation-induced ATM activation, raising the possibility that short term topical administration of retinoic acid-related pharmacons may improve DNA damage repair in skin and reduce the severity of radiation dermatitis." (PMID 28250390, 2014).
renal carcinoma (2 papers, 2021 to 2024). A carcinoma arising from the epithelium of the renal parenchyma or the renal pelvis. "Here, we describe that as a single agent, CX-4945 moderately induced cell death in VHL-deficient renal cancer cells but unexpectedly, triggered a strong ATM upregulation, providing a potential link between CK2 and ATM pro-survival pathways." (PMID 33540838, 2021). "Combined inhibition of CK2 and ATM eliminated VHL-deficient renal carcinoma cells by increasing NOX4-mediated ROS production." (PMID 33540838, 2021). "Thus, HIF-2α acts as a mediator that potentiates CK2 and ATM inhibition to induce cytotoxicity in VHL-deficient renal carcinoma cells." (PMID 33540838, 2021). "Here, we demonstrated that inhibiting CK2 with the clinically relevant inhibitor CX-4945 in VHL-deficient renal cancer cells triggered a strong activation of phospho-ATM, suggesting that the benefit resulting from the combination of CK2 and ATM inhibition may be synergistic." (PMID 33540838, 2021). "A patient with renal cancer and recurrent SPGB carried an ATM nonsense mutation and was still alive at the moment of last observation." (PMID 39684714, 2024). "Mechanistically, these results suggest that the combined inhibition of CK2 and ATM in renal cancer cells triggers an HIF-2α/NOX4-dependent ROS overproduction, leading to cellular damages and ultimately to Caspase-mediated irreversible cell death." (PMID 33540838, 2021). "Among the effective combinations identified from this screen, we found that a novel combination, pairing the CK2 inhibitor CX-4945 with the ATM inhibitor KU-60019, dramatically enhanced cell death in VHL-deficient renal carcinoma cells." (PMID 33540838, 2021). "Importantly, our findings reveal a selective killing of VHL-deficient renal carcinoma cells and provide a rationale for a mechanism-based use of combined CK2/ATM inhibitors for improved patient care in metastatic VHL-ccRCC." (PMID 33540838, 2021). "Collectively, these experiments suggest that HIF-2α-dependent vulnerability to combined inhibition of ATM and CK2 in VHL-deficient renal carcinoma cells may rely on a functional CK2–HIF-2α interaction." (PMID 33540838, 2021). "Finally, transcriptome profiling of VHL− 786-O MCTS treated with our drug combination not only confirms our results but also opens perspectives to explore additional mechanisms driving apoptosis in VHL-deficient renal carcinoma cells upon cooperative blockade of CK2 and ATM kinases." (PMID 33540838, 2021). "Since different VHL status in renal carcinoma cells have been shown to affect their drug sensitivity in hypoxic conditions, we stably reintroduced VHL into 786-O VHL-deficient cells and evaluated their sensitivity to the CK2 and ATM inhibitors under low oxygen concentration (1.5%) (Figure 1C1,C2)." (PMID 33540838, 2021).
Serous carcinoma (2 papers, 2021 to 2025).
soft tissue tumor (2 papers, 2021 to 2024). "Among these, BRCA2, ATM, and PALB2 genes had higher mutation rates of ≥4%, while in mCRPC, 19.3% of aberrations in BRCA2, BRCA1, and ATM genes were found in bone or soft tissue tumor biopsies that were substantially more frequently compared to those in primary PC tissues." (PMID 34769200, 2021).
spinal muscular atrophy (2 papers, 2018 to 2024). A motor neuron disease that affect the muscles, and characterized by muscle weakness and atrophy resulting from progressive degeneration and irreversible loss of the anterior horn cells in the spinal cord (i.e., lower motor neurons) and the brain stem nuclei. "The large size of the ATM protein has so far eluded viral vector-based gene therapy, which has shown some promise in spinal muscular atrophy and Tay–Sachs disease." (PMID 39764161, 2024).